BCL2 (BCL2 apoptosis regulator)
Diseases named in the same sentence as BCL2 in open-access papers (continued):
Sharing a sentence is not in itself a finding about the gene and the disease.
cancer (continued). "BCL2 is also a direct target of miR-1290 and miR-206 in non-small cell lung cancer (NSCLC), with miR-1290 mediated silencing of BCL2 has been reported to regulate the apoptotic effect to asiatic acid—a putative anti-cancer agent—in A549 cells." (PMID 29361709, 2018). "The revealed synergistic pro-apoptotic effect, depending on both death receptors (TRAIL-R1/DR4, TRAIL-R2/DR5) and caspases (caspase-8, -9 and -3) activation, was lethal on cancer cells but not on normal human intestinal epithelial cells (HIEC), and was inhibited by Bcl-2 expression." (PMID 26771233, 2016). "However, longer incubation of WHCO1 and MDA MB 231 cells with WJ-MSCs did not result in sustained downregulation of PCNA, BCL-2, MMP-2, and c-MYC gene expression in the cancer cells indicating that the effect of coculture is transient." (PMID 26880967, 2016). "The BCL2 inhibitors ABT-737 and ABT-199 had no inhibitory effects on miRNA-17 and miRNA-20b expression; these miRNAs were investigated because they were significantly upregulated in the cancer miRNA array." (PMID 26394044, 2015). "Consequently, detailed knowledge of the sensitivity of the targeted cancer type with respect to non-malignant tissue is crucial for the development and for administration of BH3 mimetics that typically target more than one Bcl-2 molecule." (PMID 22292048, 2012). "We observed no expression of anti-apoptotic BCL-2 protein in either male or female extract-treated MCF-7 and T47D cells, suggesting that M. pomifera could be an excellent candidate to target BCL-2 proteins in different cancers." (PMID 38791297, 2024). "It is not clear whether GNA13 also regulates the expression of BCL2 in tumors other than GCB-DLBCL and whether the therapeutic scenario for targeting palmitoylation of GNA13 in combination with the BCL2 inhibitor holds in other types of cancer." (PMID 33423045, 2021). "In AML, unlike in lymphoid malignancies, BCL-2 gene is not rearranged, neither is it always overexpressed, but, surprisingly, this does not precluded BH3-mimetic’s efficacy, illustrating the concept of non-oncogene addiction, by which a cancer cell becomes dependent on a normal cell function." (PMID 34830763, 2021). "However, in contrast to studies in human cancer cell lines or rat VSMCs, TIMP-3 induced apoptosis in hVSMCs is via a FAS-dependent type-I apoptotic pathway, as Bcl2 over expression did not inhibit apoptosis significantly and loss of mitochondrial membrane potential was not seen." (PMID 29617412, 2018). "Consequently, the G1/S-CDK suppresser CDKN1B (p21) and pro-apoptotic proteins Bax and activated caspase-3 were upregulated, while anti-apoptotic Bcl-2 was downregulated, which were followed by cell cycle arrest at G1 and marked apoptosis in ATL-treated cancer but not non-cancer cells." (PMID 27089328, 2016). "Moreover, inhibition of BCL2 and XIAP might not induce direct antiproliferative effects in cancer cells but rather a sensitisation to exogenous apoptosis stimuli similar to chemotherapy or radiation." (PMID 22797576, 2012). "Finally, since the hydrophobic cleft of Bcl-2 was not involved in IP3R suppression, our findings indicate that ABT-199 does not interfere with IP3R regulation by Bcl-2 and its mechanism of action as a cell-death therapeutic in cancer cells likely does not involve Ca2+ signaling." (PMID 27494888, 2016).
infection (336 papers, 2004 to 2026). The state of being infected such as from the introduction of a foreign agent such as serum, vaccine, antigenic substance or organism. "The loss of Bcl‐2 production immediately after TCR signaling was confirmed in antigen‐specific OT‐I CD8+ memory T cells isolated 3 months after infection with Listeria‐OVA." (PMID 37840018, 2024). "This contrasted with the reduced association of BCL2 with BECN1 after infection of germ-free wild-type mice." (PMID 39602254, 2024). "This process is linked to a decrease in Bcl-2 expression, facilitating the completion of BoGHV4’s productive infection cycle." (PMID 38666861, 2024). "In the case of another intracellular parasite, Leishmania major, it has been shown that the infection of cells causes the overexpression of the antiapoptotic proteins Bcl-2 y Bfl-1, possibly through the ERK1/2 signaling pathway." (PMID 38112844, 2023). "Increased expression of the survival factor Bcl-2 following antibody-mediated blockade of ICOS in the chronic phase of infection has previously been implicated as a mechanism supporting increased survival of effector T cell populations in the inflamed brain." (PMID 31978191, 2020). "Vaccinia virus (VACV) strain Western Reserve gene A49L encodes a small intracellular protein with a Bcl-2 fold that is expressed early during infection and has multiple functions." (PMID 32100702, 2020). "Recent research showed that the viral G-protein-coupled receptor (vGPCR) inhibits apoptosis of endothelial cells by upregulating BCL-2 expression during infection by Kaposi sarcoma-associated herpesvirus." (PMID 25423176, 2014). "In some cases, some viruses either encode proteins homologous to Bcl-2 to inhibit apoptosis or influence Bcl-2 expression to establish a persistent infection." (PMID 22978358, 2012). "Finally, as targeted agents such as BTK and BCL-2 inhibitors continue to reshape treatment, we need a better understanding of how they influence infection risk and immune recovery over time." (PMID 40647394, 2025). "Moreover, the MSP121-specific FCRL5hi B cells sorted after resolution of the infection upregulated the anti-apoptotic Bcl2 gene, which is an additional hallmark characteristic of memory B cells." (PMID 30387712, 2018). "This increase may be caused either directly by the expression of bcl-2 in these cells or by the increase in other myeloid cell types that recruits neutrophils to the sites of infection." (PMID 27973535, 2016). "Although our above data suggested that such a protein was not a Bcl-2-family component (because Ctr-infection protected against Bcl-2-inhibitor treatment) we tested whether the association of anti-apoptotic Bcl-2-proteins with Bak would be altered upon infection." (PMID 35397654, 2022). "Furthermore, Bcl-2 isolates are more virulent than wildtype and cause infection faster." (PMID 35736101, 2022). "The infection and inflammation environment can lead to apoptosis of enterocytes and destruction of the epithelial barrier, in which Bcl-2-associated X (Bax) protein and B-cell lymphoma-2 (Bcl-2) protein, respectively, contribute to and inhibit the development of apoptosis." (PMID 35658572, 2022). "Moreover, infection with ostreid herpesvirus 1 (OsHV-1, a common virus that can cause mass mortality of oyster) or Vibrio alginolyticus, as well air exposure and heat shock, markedly altered the expressions of these Bcl-2 relatives." (PMID 28682310, 2017). "Mechanistic validation demonstrated that Gadd45 overexpression or XIAP knockdown enhanced Bax expression, inhibited Bcl-2, increased apoptosis rates, and consequently significantly reduced intracellular bacterial load at 24 h post-infection." (PMID 41011363, 2025). "A. apis employs multi-level modulation of the host apoptosis pathway (Caspase-3/Bcl-2/Bax axis) to adapt to the infection microenvironment, while demonstrating a dynamic interplay between host apoptotic status and pathogen virulence factor gene expression." (PMID 41009106, 2025).
infection (continued). "The overall incidence of infection was similar between patients treated with BTKi and BCL2 inhibitors (19.8% versus 17.4%)." (PMID 39796746, 2025). "During early infection, expression of both anti- and pro-apoptotic genes (e.g., Bax and Bad) declines, yet the anti-/pro-apoptotic Bcl-2 ratio rises, paralleling reduced host–cell apoptosis." (PMID 41011470, 2025). "Of particular note, in macrophage infection models, the Mb1 strain significantly delays host apoptosis by markedly upregulating B-cell lymphoma 2 (Bcl-2) expression and inhibiting caspase-3, -6, and -9 activity." (PMID 41011363, 2025). "It was found that infection with E. tenella increased the levels of phosphorylated proteins P65 and I-κBα and the production of apoptotic protein Bcl-2." (PMID 41475173, 2025). "In contrast, in mid- to late infection, Bcl-2, Bcl-XL, Bax, Bak, Bid, Bad, and HK-II rise sharply; the anti-/pro-apoptotic ratio falls, and host–cell apoptosis surges." (PMID 41011470, 2025). "Comparison of expression difference between 24 and 48 hr post-infection showed a significant bcl2 expression difference in infected A549 by sensitive (rank of difference: -0.62; P=0.009) and XDR (rank of difference: -0.4; P=0.04) strains." (PMID 38800030, 2024). "The results of immunohistochemistry showed that after infection with Listeria monocytogenes, the expression of Bax and Bcl-2 proteins in the uterus was upregulated, but their distribution and location did not change significantly." (PMID 39220769, 2024). "In the liver, CTLA-4 (P = 0.0473), TCR (P = 0.0470), ICOS (P = 0.0382), CD28 (P = 0.0072) and Bcl-2 (P = 0.0462) were upregulated in undernutrition 75% + infection group at the 5th week post-infection." (PMID 38185681, 2024). "Apoptosis acts as an important defense mechanism of host against infection, in which caspase 8, caspase 3, Bcl-2 and Bax play key roles." (PMID 38439110, 2024). "To determine the specific mechanism, we examined the levels of apoptosis-related genes (BAX, APAF-1, TNF-α, Caspase-9, Caspase-3, and BCL-2) in EBL cells following infection with M. bovis." (PMID 39308873, 2024). "Compared to the parental strain, ΔVceA decreased Caspase3 (pro-apoptotic) expression at 24h post-infection, increased Bcl-2 (anti-apoptotic) expression at 12h and 24h post-infection, and decreased the percentage of apoptotic cells at 24h post-infection." (PMID 39507949, 2024). "Our study revealed that infection led to a downregulation of Bcl2 transcription levels (P < 0.01), whereas treatment with MCH restored the transcription levels of Bcl2 (P < 0.05)." (PMID 38654385, 2024). "Viruses have adapted to modulate apoptosis and autophagy in response to infection and their genomes frequently contain Bcl-2 genes." (PMID 38932171, 2024). "As expected, total levels of BCL2 were similar and p-BCL2 levels increased upon infection of both wild-type and Becn1F121A organoids." (PMID 39602254, 2024). "This study indicates that the mitochondrial apoptotic pathway is activated during infection with upregulation of proapoptotic Bax and anti-apoptotic Bcl2." (PMID 38255873, 2024). "We showed that the proapoptotic Bax and the anti-apoptotic Bcl-2 are significantly up-regulated in infection." (PMID 38255873, 2024). "Biomarkers of the Bax and Bax/Bcl-2 ratio promote more intense apoptosis after infection with the Lagovirus europaeus GI.2 genotype." (PMID 38516020, 2024). "We demonstrated a decrease in antiapoptotic Bcl-2 and an increase in proapoptotic Bax during L. europaeus GI.1 and GI.2 genotype infection in four tissues of rabbits." (PMID 38516020, 2024). "Following infection by all sensitive and resistant strains, bcl2 and rb1 expressions were statistically significantly up-regulated, while bad and bax expressions were significantly down-regulated 24 and 48 hr post-infection." (PMID 38800030, 2024).
infection (continued). "In undernutrition 75% + infection group, except for Bax, the rest of the genes were upregulated; especially Bcl-2, Tim-3 and TCR were upregulated the most." (PMID 38185681, 2024). "Biomarkers of the Bax and Bax/Bcl-2 ratio promote more intense apoptosis after infection with the L. europaeus GI.2 genotype." (PMID 38516020, 2024). "After 12 h of PEDV infection, the expression level of Bcl-2 protein decreased (p < 0.05), and at 18 h and 24 h post-infection, the decrease in Bcl-2 protein expression was more marked (p < 0.01)." (PMID 38396878, 2024). "Compared to the control, the relative protein expression levels of caspase-3 and Bax were significantly increased, and the relative expression of Bcl-2 protein decreased significantly in IEC-6 cells following infection with Pg-LPS and Pg respectively." (PMID 38731952, 2024). "We showed that the Bax/Bcl-2 ratio promotes apoptosis during infection with L. europaeus—two genotypes—and was more strongly expressed (2–3 times) during GI.2 infection." (PMID 38516020, 2024). "As compared with strains with the New-1 genotype (INHR, RifR, MDR, and XDR), the Beijing genotype (sensitive isolate) significantly increased and decreased anti-apoptotic (bcl2 and rb1) and pro-apoptotic genes (bad and bax) 24 and 48 hr post-infection." (PMID 38800030, 2024). "The finding was that at 12 hours after infection, the expression of Bcl-2 and BAX was similar, but there was an increase in the expression of PARP in infected cells." (PMID 37186587, 2023). "Contrarily, the infection with M. tuberculosis can also induce the overexpression of Bcl-2 and Mcl-1 to inhibit host cell apoptosis." (PMID 38112844, 2023). "As a result, the relative expression of Bax to Bcl-2 was higher at 36 and 48 h after infection in the infected rabbits compared to healthy control." (PMID 38333074, 2023). "Data showed that functional inhibition of BCL2 caused increased nitric oxide (NO) response and reduced parasite burden in monocytes after L. major infection, confirming the role of BCL2 during infection." (PMID 38143766, 2023). "BCL2 and Caspase-3 gene expression were upregulated because of the infection induced by E. papillata." (PMID 36875142, 2023). "In particular, western blot analysis showed a reduction of Bcl-2 and BcL-XL proteins starting 24 h post-infection, confirming the pronounced mitochondrial damage exhibited by FeHV-1-infected cells." (PMID 38087282, 2023). "It was also showed that mice immunized with gamma-irradiated Trichinella spiralis larvae are protected against infection, which leads to reduced muscle damage, Myogenin and Bcl-2 expression." (PMID 36538023, 2023). "We did not detect significant differences in mRNA expression of anti-apoptotic bcl2 among HKDMs infected with any strains or at any time of infection (top left)." (PMID 37796003, 2023). "Further analysis revealed that during early infection there is an enrichment in apoptosis-inducing factor-mediated signaling, while only the anti-apoptotic factors survivin and Bcl-2 (B cell lymphoma-2) remains after nurse cell formation." (PMID 36538023, 2023). "All infections and related controls were also subjected to Western blot analysis to assess the expression of apoptotic markers (caspase 3-8-9, Bcl-2, Bcl-xL, NF-κB)." (PMID 38087282, 2023). "Real-time PCR assay revealed that RSV-A2 infection significantly elevated the Bax and decreased the Bcl2 expression." (PMID 37641004, 2023). "Chlamydia trachomatis upregulates MCL-1 to inhibit Bax-induced apoptosis, and M. tuberculosis upregulates BCL-2 in macrophages during infection to prevent apoptosis." (PMID 37530530, 2023). "There were no statistically significant alterations in proliferation (Ki-67) and in apoptosis (BCL-2) amongst the Vero and human cell lines along the infection course." (PMID 35335638, 2022).
infection (continued). "TRP120-Hh-SLiM significantly increased levels of Hh target, anti-apoptotic protein B-cell lymphoma 2 (BCL-2), and siRNA knockdown of BCL-2 dramatically inhibited infection." (PMID 35576232, 2022). "Numerous large DNA viruses have evolved sophisticated countermeasures to hijack the premature programmed cell death of host cells post-infection, including the expression of proteins homologous in sequence, structure, or function to cellular Bcl-2 proteins." (PMID 35458468, 2022). "qPCR was used to detect the expression of apoptosis and inflammation-related genes, which showed that Caspases 3/8/9 were significantly up-regulated after infection for 36 or 48 h, and the Bcl-2/Bax ratio was significantly decreased after infection for 36 h." (PMID 35682869, 2022). "It has been reported that stress or infection can change the expressions of Bax and Bcl-2 in the gastrointestinal tract." (PMID 36077889, 2022). "Bcl-2 gene expression in the colon decreased post infection and reached a significantly lower level at 60 dpi (p < 0.01)." (PMID 35955110, 2022). "The level of Bcl-2 protein decreased as infection duration increased, with the lowest expression at 8 h." (PMID 35812882, 2022). "With the increasing infection duration, Bcl-2 expression declined steadily, with the lowest expression at 12 h." (PMID 35812882, 2022). "In our study, ISKNV infection was shown to upregulate both pro-apoptotic members Bax/Bak and anti-apoptotic members Bcl-2/Bcl-xL at the early replication stage." (PMID 35632664, 2022). "The results indicated that MRSA and MSSA treatment of MAC-T cells increased the protein expression of TNF-α, IL-6, cleavage–Caspase3, Phospho-p65, and PrP, and then the protein expression of Bcl-2 appeared to decrease slightly with the duration of infection." (PMID 35812882, 2022). "Our data showed that H37Rv infection increased the BCL-2 transcript and protein, decreased the BAX transcript, and increased phosphorylated BCL-2 at the protein level." (PMID 35631013, 2022). "CCAAT/enhancer-binding protein beta (C/EBPB), growth arrest and DNA-damage-inducible 45 beta (GADD45B), and BCL2, which are associated with cell proliferation and apoptosis, were upregulated at different time points after PCV2 infection." (PMID 35324828, 2022). "BAD is a Bcl2-associated agonist that promotes cells death, and S140 phosphorylation was upregulated in this protein following SVA infection by 1.68-fold relative to controls." (PMID 35154063, 2022). "Accordingly, a smaller fraction of ERKSEM P14 T cells expressed Bim and a larger fraction expressed Bcl-2 at Day 10 post infection." (PMID 36846018, 2022). "After confirming that DTMUV can activate caspase-9, we found that DTMUV infection of DEFs can promote the release of Cyt C from mitochondria to the cytoplasm and can also inhibit the expression of the antiapoptotic protein Bcl-2." (PMID 35799206, 2022). "Herpes-simplex virus 2 (HSV-2) and Hantaan virus both downregulate BCL-2 for a productive infection as they induce apoptosis in late-stage infection." (PMID 36569952, 2022). "The role of Bcl-xL, Bcl-2, and Bcl-w seemed to be to delay the intrinsic apoptosis induction at the same time as maintaining cell viability at the early stage of infection to enable the synthesis of progeny viral ribonucleoprotein (vRNP) in the nucleus." (PMID 33669408, 2021). "Messenger RNA levels of the autophagy-related genes were significantly elevated at most of the timepoints after infection, except for some genes (Bcl-2, Atg5, Atg12, DRAM1, and VMP1) whose transcription levels declined at 7 dpi." (PMID 33600403, 2021). "The picture that emerges regarding vMIA/vIBO suppression seems reminiscent of adenovirus-encoded viral BCL-2 antagonist E1B 19K, a function that suppresses analogous TNF-mitochondria synergy during infection." (PMID 34578288, 2021).